INS (insulin)
Diseases named in the same sentence as INS in open-access papers (continued):
Sharing a sentence is not in itself a finding about the gene and the disease.
Glucose intolerance (continued). "We used transgenic mouse models to selectively delete pericytic IL-33 expression and found that loss of this cytokine caused glucose intolerance due to impaired insulin secretion." (PMID 36967785, 2023). "In contrast, double knockout mice with β cell-specific Mfn1 and 2 deletions displayed glucose intolerance and impaired insulin secretion due to loss of mtDNA content." (PMID 37762083, 2023). "On the other hand, heterozygous carriers of PDX1 mutations are linked to MODY4, characterized by modest glucose intolerance due to compromised insulin secretion." (PMID 38333726, 2023). "The glucose intolerance was associated with changes in the miRNA profile, and insulin signaling in skeletal muscle tissues showed decreased phosphorylation of IRS-1 and Akt." (PMID 37650554, 2023). "It is recognized that gestational diabetes mellitus is a temporary glucose intolerance caused by failure of the pancreas to secrete insulin by beta cells and insulin resistance of tissues such as subcutaneous, muscle, and liver tissues." (PMID 37762934, 2023). "Puberty in rats is associated with glucose intolerance and a decrease in insulin sensitivity in both sexes." (PMID 36107617, 2022). "While people exhibiting glucose intolerance or early-stage 2DM tend to have elevated amylin levels in accordance with hyperinsulinemia, amylin levels at later stages of insulin-deficient 2DM have been described as normal or deficient." (PMID 35456307, 2022). "Paradoxically, some evidence indicates that liver and other tissues appear to be involved in TCF7L2 rs7903146T-associated glucose intolerance and insulin secretion." (PMID 35477971, 2022). "We reveal age-dependent impairment in glucose tolerance in both male and female in βOGAKO mice under normal chow diet, and that glucose intolerance in these mice was associated with defects in insulin content and insulin secretion." (PMID 36387851, 2022). "Muscle inactivity and unloading are linked to glucose intolerance and both astronauts and bedridden subjects consistently display alterations in insulin sensitivity." (PMID 36741463, 2022). "Hypothalamic ER stress activated IKKβ/NF-κB signaling, causing inflammation, glucose intolerance and central insulin and leptin resistance." (PMID 36188456, 2022). "Both drugs cause reversible toxicity in pancreatic beta cells, especially in the early post-transplantation period, directly affect the transcriptional regulation of insulin expression, cause glucose intolerance and inhibit lipolysis." (PMID 36402951, 2022). "A single allele of p300 or CBP rescues glucose intolerance and the loss of skeletal muscle insulin-stimulated glucose uptake seen in PCKO mice." (PMID 34813504, 2022). "CX3CR1-deficient mice exhibit glucose intolerance mainly due to beta cell dysfunction, while fractalkine treatment improves glucose tolerance and increases insulin secretion in wild-type mice." (PMID 35871167, 2022). "Glucose intolerance is often associated with aging, and elevated levels of both glucose and insulin have been observed in the elderly after oral glucose challenge testing." (PMID 36564463, 2022). "Adult female mice exposed to an obesogenic but normoglycemic intrauterine environment and fed an HFD in adulthood from the 15th week of age develop glucose intolerance at 50 weeks of age, which is associated with a decrease in the amount of insulin secreted." (PMID 35216239, 2022). "Urea, another metabolite of arginase-mediated L-arginine metabolism, has been demonstrated that it is implicated in β-cell dysfunction, insulin sensitivity reduction, and glucose intolerance." (PMID 36338341, 2022). "Compared to normal HFD-fed mice, GPR43-deficient mice fed a HFD developed glucose intolerance with defects in insulin secretion." (PMID 34975320, 2022). "Our findings suggest that circulating sEVs contribute to the attenuated insulin secretion and more pronounced glucose intolerance which underlie the pathology of GDM." (PMID 36239315, 2022).
Glucose intolerance (continued). "In adult mice, RFX3-dependent cilia loss leads to reduced insulin content and secretion, as well as fasting hyperglycemia and glucose intolerance." (PMID 35813631, 2022). "The mechanism underlying the decrease in insulin secretion and glucose intolerance is thought to be ATF4 activation caused by increased mTORC1 activity in pancreatic β-cells." (PMID 35625542, 2022). "Researches have shown that overexpression of Adra2a in β cells can lead to impaired insulin secretion and glucose intolerance and increase the risk of T2D." (PMID 36420091, 2022). "Children born from mothers with energy deficiency during pregnancy have reduced birth weight, impaired insulin secretion at adulthood, and a predisposition to develop glucose intolerance." (PMID 35216239, 2022). "As skeletal muscle accounts for roughly 70% of insulin stimulated glucose clearance, we sought to address the cause for Val-induced glucose intolerance in muscle." (PMID 35418570, 2022). "In accordance with the apparent repression of liver glucose metabolism in LW, glucose intolerance, associated with higher basal levels of insulin, was observed in LW in this species." (PMID 35457071, 2022). "In the current study, the muscle CSE deficiency led to glucose intolerance and poor insulin sensitivity, and reduced GLUT4 expression level and IRS/PI3K/Akt signaling pathway." (PMID 36358588, 2022). "It has been reported gestational glucose intolerance can be classified into two subgroups as insulin resistant group and insulin sensitive group, which are at differential risk for adverse outcomes." (PMID 35135562, 2022). "In mouse studies, protein tyrosine kinase 2 beta (PTK2B) was found to play a critical role in the differentiation of beige adipocytes, CD47–/– knockout resulted in resistance to insulin desensitisation, glucose intolerance and diet-associated weight gain." (PMID 36151087, 2022). "Membrane cholesterol content due to hypercholesterolemia has been associated with low insulin secretion and glucose intolerance." (PMID 36005626, 2022). "Late intake of food is known to disrupt the body’s circadian rhythms, affecting insulin sensitivity and predisposing to glucose intolerance." (PMID 36361482, 2022). "When compared to control mice, Atg5-deficient CD11c+ mice exhibit increased glucose intolerance and decreased insulin sensitivity when fed HFD." (PMID 35301333, 2022). "Since β-AR is expressed in the pulmonary bronchus and pancreas, β-AR blockers cause bronchial smooth muscle contraction and inhibition of insulin release, leading to bronchospasm and glucose intolerance." (PMID 35148678, 2022). "Exosomes from the plasma of GDM patients also cause glucose intolerance, decreased glucose-induced insulin secretion, and poor insulin responsiveness." (PMID 35517798, 2022). "A recent prospective cohort study demonstrated that PA caused decreased insulin secretion and an increased rate of insulin clearance, which lead to glucose intolerance." (PMID 35187110, 2021). "Subsequently, chemerin deficiency causes glucose intolerance mainly due to increased hepatic glucose production and impaired insulin secretion." (PMID 34007846, 2021). "Glucose intolerance and loss of insulin sensitivity were observed in young and elder mice perinatally exposed to BPA." (PMID 34063694, 2021). "Females with GDM exhibit glucose intolerance, which is usually associated with an increase in insulin and amylin secretion." (PMID 34686739, 2021). "Our data suggest that excessive NaCl intake accompanied by a HFD exacerbates glucose intolerance, with impairment in insulin secretion caused by the attenuation of expansion of β-cell mass in the pancreas." (PMID 33730054, 2021). "This suggests that the error‐prone mutation on an HFD results in reduced insulin production that contributes to glucose intolerance and lipid accumulation." (PMID 34096683, 2021).
Glucose intolerance (continued). "Hypoxia is known to cause glucose intolerance, whilst ongoing low-grade inflammation leads to insulin insensitivity." (PMID 34512552, 2021). "Factors that reduce serotonin synthesis and perturb HTR2B signaling are associated with decreased β-cell number, impaired insulin secretion, and gestational glucose intolerance in mice." (PMID 33772108, 2021). "Literature data indicate that impaired insulin secretion, impaired insulin sensitivity and glucose intolerance are strongly associated with elevated plasma levels of saturated FFAs (including palmitic and stearic acid)." (PMID 34209638, 2021). "This was associated with low glucose-induced insulin secretion and glucose intolerance, as compared to the normal phenotype (nW/sW model)." (PMID 33525575, 2021). "As observed in the IA2 deficient mice, IA2β deficient mice also exhibit a mild glucose intolerance and impaired insulin secretion." (PMID 34071721, 2021). "To uncover the underlying mechanism of vitamin B6 deficiency-induced glucose intolerance, we performed in vivo glucose-stimulated insulin secretion (GSIS)." (PMID 33772108, 2021). "The study on transgenic mice with overexpression of GDNF in glial cells revealed that they are protected from obesity, glucose intolerance, and resistance to insulin caused by high-fat meals." (PMID 34512552, 2021). "Our findings suggest that vitamin B6 deficiency-induced gestational glucose intolerance involves additional mechanisms that are complex and insulin independent." (PMID 33772108, 2021). "Together, these data show that mice lacking Efnb1 in POMCprog display altered excitability of POMCprog and develop glucose intolerance that is associated with impaired insulin secretion and impaired parasympathetic nerve activity." (PMID 33253166, 2020). "Results of this analysis showed individuals with a high allele score experienced greater glucose intolerance as shown by significant differences in glucose and insulin excursion as well as a trend in the ISI with p = 0.07." (PMID 33339359, 2020). "Hyperkalemia increases insulin secretion by depolarizing pancreatic beta cells, whereas hypokalemia inhibits insulin secretion and is associated with glucose intolerance." (PMID 32789612, 2020). "This protein reduces insulin sensitivity in the liver and causes glucose intolerance and IR after injection in control mice." (PMID 33375647, 2020). "Experimentally, high-fructose diets have been shown to lead to moderate hypertension and glucose intolerance, associated with increased levels of plasma insulin, cholesterol and triglycerides." (PMID 32521542, 2020). "Prolonged anesthesia with sevoflurane causes glucose intolerance due to diminished insulin output in response to blood glucose elevation during surgery." (PMID 32240260, 2020). "IGF-1R conditional knockout in β-cells (βIGF-1KO) resulted in a progressive loss of glucose-stimulated first phase insulin secretion and glucose intolerance, due to aberrant β-cell proliferation and reduced mass by apoptosis." (PMID 32150819, 2020). "Disposition index can show the relative contribution of Si and insulin secretion as causes of glucose intolerance." (PMID 31620090, 2019). "It was shown, that genetically CerS2-deficient mice displayed glucose intolerance even with physiological insulin secretion from the β-cell of the islets of Langerhans." (PMID 31496996, 2019). "Changes in the activity of this transporter are associated with impaired response to insulin and contribute to the progression from glucose intolerance to type 2 diabetes." (PMID 31619721, 2019). "To conclude, we showed that in the diurnal rodent Arvicanthis ansorgei acute exposure to bALAN causes glucose intolerance, reduced insulin secretion and increased consumption of sugar, especially in males." (PMID 31646762, 2019). "At p90, CR group showed a significant increase in body weight gain and plasma insulin levels associated with slight glucose intolerance." (PMID 30845245, 2019).
Glucose intolerance (continued). "Young fat-specific IR-deficient mice show a normal response to glucose and insulin injection but are protected from age-related glucose intolerance and insulin resistance." (PMID 30837656, 2019). "In patients in whom the reduced Si is the main cause behind glucose intolerance the reduction of GH/IGF-1 induced by the SSA would increase Si more than the direct insulin inhibition with the result of improved glucose tolerance." (PMID 31620090, 2019). "It is not surprising then that AP exposure (known to increase adiposity) is linked with impaired insulin sensitivity and glucose intolerance." (PMID 31555747, 2019). "Impaired β-cell function and insulin secretion have also been implicated to contribute to glucose intolerance in these patients." (PMID 30948746, 2019). "The TLR4-mediated pathway of innate immunity is linked to inhibition of insulin signaling, consistent with the effects of carrageenan on glucose intolerance." (PMID 31179345, 2019). "Glucose intolerance and impairment of insulin secretion are associated with a high risk to develop dementia or AD." (PMID 31551793, 2019). "In conclusion, short-term (two weeks or less) glimepiride treatment in mice caused significant impairment of insulin secretion, resulting in profound glucose intolerance." (PMID 30510962, 2018). "Taken together with the in vivo studies, these ex vivo analyses support a strong age-dependent association between WD-induced insulin secretion and glucose intolerance." (PMID 30546031, 2018). "Impaired insulin secretion and resistance was the relevant link between T2D and AD, and the glucose intolerance also seems to be associated with increased risk of AD." (PMID 29263141, 2018). "Pancreas-specific loss of Adrb2 results in glucose intolerance and impaired glucose-stimulated insulin secretion, which surprisingly, was observed only in female mice." (PMID 30303066, 2018). "HFD caused glucose intolerance and insulin insensitivity, with HFD mice demonstrating higher blood glucose in response to glucose injection (main effect of diet, p < 0.05)." (PMID 30619085, 2018). "Vitamin D receptors, vitamin D binding protein, and some allelic gene variations have been shown to be linked to insulin sensitivity, insulin secretion, glucose intolerance and, inflammation." (PMID 29449867, 2018). "This normalization of plasma triacylglycerol in the BezaDexa group also paralleled the attenuation of glucose intolerance and prevention of any alterations in the peripheral insulin sensitivity caused by GC treatment." (PMID 30532777, 2018). "Hypomagnesemia is one of the proposed mechanisms for calcineurin-associated glucose intolerance, due to magnesium which is essential for glucose transport and pancreatic insulin secretion, and is involved in the post-receptor insulin signaling." (PMID 30624499, 2018). "In adult mice, fed hyperglucagonemia is even more marked than in young mice and is associated with small glucose intolerance, and an increase in plasma insulin measured 30 min after i.p. glucose injection." (PMID 29416045, 2018). "Rictor null mice exhibits glucose intolerance caused by a reduction in β-cell mass, beta-cell proliferation, pancreatic insulin content, and glucose-stimulated insulin secretion." (PMID 30011848, 2018). "In humans, hypophosphatemia has been associated to glucose intolerance due to tissue insensitivity to insulin and glucose disposal rate has been reported to increase after phosphate infusion." (PMID 30322116, 2018). "Certain substrains of C57BL/6 mice contain a spontaneously occurring inactivating Nnt mutation and display glucocorticoid deficiency along with glucose intolerance and reduced insulin secretion." (PMID 29046340, 2018). "Glucose intolerance caused by dexamethasone treatment occurred parallelly to a significant decrease in the insulin sensitivity as observed by the ipITT data obtained on the 37th day." (PMID 30686986, 2018).
Glucose intolerance (continued). "The loss of muscle mass contributes to glucose intolerance and promotes gluconeogenesis by reducing the quantity of the main cellular target for insulin." (PMID 30274215, 2018). "C57BL/6J mice have a spontaneously inactivating Nnt mutation and display glucocorticoid deficiency along with glucose intolerance and reduced insulin secretion." (PMID 30576384, 2018). "Taken together, these findings indicate that increased Nmnat3 expression alleviates aging‐associated glucose intolerance by increasing insulin sensitivity." (PMID 29901258, 2018). "Loss of Adrb2 in neonatal β-cells results in glucose intolerance and impaired insulin secretion in female mice." (PMID 30303066, 2018). "Low BW, like maternal GDM, has been inversely associated with glucose intolerance and insulin sensitivity during childhood and increased risk for CVD later in life." (PMID 29176960, 2017). "There findings suggest that maternal chromium restriction diet results in glucose intolerance in male offspring through alterations in DNA methylation which is associated with the insulin signaling pathway in the mice livers." (PMID 28072825, 2017). "SERCA2 deficiency occurs in human Darier–White disease, leading to glucose intolerance, decreased insulin secretion, reduced β-cell proliferation, and increased β-cell ERS." (PMID 29046367, 2017). "We attempt to explore the mechanisms underlying pathways from CM to glucose intolerance and reduced insulin sensitivity because it allows for the development of more specific targets for the subsequent T2D." (PMID 28713332, 2017). "The Wfs1-ex5-KO232 rats display glucose intolerance that is steadily exacerbated with age and is accompanied by a reduction of beta cell mass suggesting that a deficit in insulin release underlies their glucose intolerance." (PMID 28860598, 2017). "We found that DJ-1 deficiency increased energy expenditure and improved insulin sensitivity whereas transgenic expression of DJ-1 induced reduced energy consumption and glucose intolerance by alteration BAT activity." (PMID 28224045, 2017). "In the present study, we showed that mice deficient in the Rab27a effector, exophilin-8, exhibit glucose intolerance and impaired insulin secretion in vivo." (PMID 28673385, 2017). "Impairments in the action of insulin can lead to impaired fasting glucose or glucose intolerance which are key risk factors for the development of diabetes." (PMID 29107286, 2017). "To explore the cause of glucose intolerance in Fh1βKO mice, we examined insulin secretion from the perfused pancreas." (PMID 28954230, 2017). "An association of impaired insulin secretion and glucose intolerance with short uncapped telomeres has been established." (PMID 28944611, 2017). "Impairment of insulin secretion is the most important factor to predict glucose intolerance in NAFLD; severity of histological findings is associated with insulin sensitivity independent of adiposity in NAFLD." (PMID 28878826, 2017). "Overexpression of MUP1 can lower blood glucose levels and cause glucose intolerance with enhanced insulin sensitivity." (PMID 28738076, 2017). "Nevertheless, these findings were corroborated by another study where long term KD feeding in mice led to glucose intolerance that was associated with insufficient insulin secretion from β-cells, potentially due to a decrease in β-cell mass." (PMID 28534852, 2017). "Functionally, inhibiting glucose sensing in the ARH reduced insulin secretion and led to glucose intolerance, demonstrating a causal relationship between the innervation and pancreatic secretory function." (PMID 28469281, 2017). "Breastfeeding has been associated with lower FPG and insulin, and a lower prevalence of glucose intolerance 6–9 weeks post-partum." (PMID 27285104, 2016). "This is surprising; previous studies associated elevated PTH levels with glucose intolerance and insulin insensitivity." (PMID 27362844, 2016).